CCND1 (cyclin D1)
Diseases named in the same sentence as CCND1 in open-access papers (continued):
Sharing a sentence is not in itself a finding about the gene and the disease.
colorectal cancer (278 papers, 2002 to 2026). A primary or metastatic malignant neoplasm that affects the colon or rectum. "No human disease has yet been associated with variants in CCND1; however, a number of studies have identified a common CCND1 polymorphism (c.870G>A, rs603965) that increases susceptibility to colorectal cancer and multiple myeloma." (PMID 37510349, 2023). "One possible explanation of the anticancer properties of capsaicin in colorectal cancer is associated with Cyclin D1 degradation and 20S proteasome activity." (PMID 33379302, 2020). "Cyclin D1 is associated with ubiquitin and then relocated to the 26S proteasome, playing a main role in colorectal cancer by inducing the transition through the restriction point in the G1 phase." (PMID 33379302, 2020). "It seems that the impact of CCND1 A870G polymorphism on the risk of colorectal cancer is likely to vary in different racial and ethnic groups with different allelic frequency of the A allele." (PMID 29511472, 2017). "A common adenine-to-guanine substitution polymorphism (A870G) at codon 241 in exon 4 of the CCND1 gene influences on risk of the early-age onset in several malignant neoplasms, including colorectal cancer." (PMID 29511472, 2017). "The aim of this study is to demonstrate the role of CCND1 gene polymorphism, A870G, in susceptibility to sporadic colorectal cancer in Iranian population." (PMID 29511472, 2017). "A large number of epidemiological studies have assessed the potential correlation between the CCND1 G870A polymorphism and the risk of colorectal cancer (CRC), but their findings have been inconsistent." (PMID 29049220, 2017). "Especially, cyclin D1 overexpression has been overexpressed in 68.3 % of human colorectal cancer case and deregulation of cyclin D1 has been associated with colorectal tumorigenesis." (PMID 27670681, 2016). "In contrast, the patient harbored a second variant in CCND1 (rs9344) that is inversely correlated with overall survival in colorectal cancer patients treated with Cetuximab43." (PMID 27723755, 2016). "Meta-analysis of 10 studies showed that high cyclin D1 expression was associated with poor DFS in colorectal cancer patients (HR: 0.60, 95% CI: 0.44–0.82, P = 0.001, and I2 = 23.7%, P = 0.225 for heterogeneity)." (PMID 24728073, 2014). "Meta-analysis of the association between cyclin D1 expression and clinicopathological features of colorectal cancer." (PMID 24728073, 2014). "A large number of genes have been identified as β-catenin targets, including c-myc and cyclin D1, which are implicated in the development of colorectal cancer." (PMID 22460269, 2012). "A comprehensive search was conducted to identify eligible studies of the CCND1 G870A polymorphism and colorectal cancer risk." (PMID 22606291, 2012). "We applied the Venice criteria to evaluate the overall evidence of an association between the CCND1 G870A polymorphism and colorectal cancer susceptibility." (PMID 22606291, 2012). "Numerous epidemiological studies have evaluated the association between the CCND1 G870A polymorphism and the risk of colorectal cancer." (PMID 22606291, 2012). "ERK translocates to the nucleus and phosphorylates transcription factors that regulate genes controlling cell proliferation, including cyclin D1 that is overexpressed in 30–50% of colorectal carcinomas and is associated with a poor prognosis." (PMID 19997103, 2010). "There have been a number of studies that have focused on the cyclin D1 870 G>A polymorphism and colorectal cancer development however these reports are somewhat conflicting." (PMID 18822177, 2008). "The CCND1 A870G polymorphism appeared to confer a modest, although statistically insignificant, increase in the risk of colorectal cancer in women (OR, 1.59; 95% CI, 0.98–2.57)." (PMID 16495921, 2006). "The CCND1 polymorphism appeared to confer a modest elevation in the risk of colorectal cancer among women." (PMID 16495921, 2006).
colorectal cancer (continued). "A common adenine to guanine polymorphism (A870G) in the CCND1 gene has been associated with a longer-life protein and an increased risk of colorectal cancer and adenoma in some studies." (PMID 16495921, 2006). "Previous studies reported a younger age of onset for colorectal cancer for subjects with HNPCC who possessed the AA or GA CCND1 genotype or the presence of the variant truncated CCND1 transcript (preferentially encoded by the A870G genotype)." (PMID 16495921, 2006). "We also assessed the associations of several dietary and lifestyle factors with risk of colorectal cancer or adenoma stratified by CCND1 genotype." (PMID 16495921, 2006). "The strongest evidence, to date, has linked the CCND1 A870G polymorphism with an increased risk of colorectal cancer and adenoma in many though not all studies." (PMID 16495921, 2006). "In the present study, the GA or AA CCND1 genotype was associated with a borderline significant increase in the risk of colorectal cancer only among women." (PMID 16495921, 2006). "The correlation between abnormal expression of β-catenin and overexpression of target genes, Cyclin D1 and c-Myc, in pancreatic cancer and colorectal carcinoma have been previously evaluated and correlated with loss of tumor differentiation, metastasis and prognosis." (PMID 34804623, 2021). "Thus, cyclin D1 has been regarded as a hallmark of colorectal cancer and a potential target of colorectal cancer treatment." (PMID 30736789, 2019). "However, a significant association between CCND1 SNP and increased risk for breast, esophageal, and colorectal cancer was found on subgroup analysis." (PMID 30361291, 2018). "Thus, CCND1 G870A (rs9344) polymorphism has a potential to be served as a prognostic biomarker for breast, esophageal, and colorectal cancer in Indian population." (PMID 30361291, 2018). "Therefore, Cyclin D1, E and B1 overexpression was positively linked to WT parafibromin-mediated G2 arrest of colorectal cancer cells." (PMID 28223542, 2017). "Association between CCND1 G870A polymorphism and colorectal cancer." (PMID 29049220, 2017). "Distribution of CCND1 G870A genotype and Allele among colorectal cancers and controls." (PMID 29049220, 2017). "Of the remaining eight variants, two variants were also detected in disease-related genes: p.G204R in HDAC4 for brachydactyly-mental retardation syndrome, and p.276del in CCND1 constituting a susceptibility factor for colorectal cancer and a modifier for von Hippel-Lindau disease." (PMID 24637876, 2014). "Through literature search and selection, a total of 22 publications including 6157 cases and 8198 controls comparing the CCND1 G870A polymorphism and colorectal cancer susceptibility were identified based on MOOSE (Meta-analysis Of Observational Studies in Epidemiology) guidelines." (PMID 22606291, 2012). "The available evidence demonstrates that the CCND1 870A allele might be a low-penetrant risk factor for colorectal cancer." (PMID 22606291, 2012). "Meta-analysis of the association between the CCND1 G870A polymorphism and colorectal cancer risk." (PMID 22606291, 2012). "The positive influences of CCND1 870A allele are thus consistent with one another, even though they do not concord with the sole published study having analyzed the impact of CCND1 A870G polymorphism on the outcome of advanced colorectal cancer patients receiving cetuximab therapy." (PMID 22117530, 2011). "In HCT116 colorectal cancer cells, which harbour constitutive activation of canonical Wnt signalling, ectopically expressed active Rac1 associated with TBEs within the promoters of Wnt-responsive genes c-Myc and Cyclin D1." (PMID 18826597, 2008). "In conclusion, we have shown that the 870 G>A polymorphism in cyclin D1 may be associated with endometrial cancer risk and provided support for an association with colorectal cancer risk." (PMID 18822177, 2008).
colorectal cancer (continued). "We therefore examined the influence of the CCND1 A870G polymorphism on the risk of colorectal cancer and adenoma in three large prospective cohort studies, the Nurses’ Health Study (NHS), the Health Professionals’ Follow-Up Study (HPFS), and the Physicians’ Health Study (PHS)." (PMID 16495921, 2006). "In summary, our results suggest that the risk of both colorectal cancer and adenoma associated with a family history of colorectal cancer may be augmented by the CCND1 A870G genotype." (PMID 16495921, 2006). "Notably, among postmenopausal women in the NHS, a reduced risk of colorectal cancer or adenoma associated with current oestrogen use was restricted to women with the GA or AA CCND1 genotype." (PMID 16495921, 2006). "Use of cyclin D1 as a pharmacodynamic (PD) endpoint biomarker of SHetA2 chemoprevention activity was supported by the observation of a SHetA2 dose-dependent decrease of polyp cyclin D1 levels in association with reduction of the number and sizes of polyps in the APCmin/+ model of colorectal cancer." (PMID 29273857, 2018). "Although, no experimental data is available to date about the interaction of miR-497-CCND1 in colorectal cancer, the overexpression of cyclin D1 mRNA might cause by the underexpression of miR-497 in colorectal adenoma and cancer by posttranscriptional silencing." (PMID 28289479, 2017). "Although a number of studies have described that the CCND1 870A allele is associated with susceptibility to various tumors, results of recent meta-analysis indicated that CCND1 G870A polymorphism is a potential risk factor only in the development of brain, lung, breast, and colorectal cancers." (PMID 25851350, 2015). "Protocatechualdehyde (PCA) exerted anti-cancer activity by reducing the protein level of cyclin D1 through the regulation of HDAC2 in colorectal cancer cells." (PMID 40076435, 2025). "Mechanistically, MG53 functions as an E3 ligase of cyclin D1, thereby suppressing tumor growth in mouse models with xenograft tumors as well as carcinogen-induced colorectal cancer." (PMID 37414783, 2023). "KDM3A/B substantially regulates the expression of Wnt or beta-catenin target genes c-Myc, MMP9 (matrix metallopeptidase 9), and cyclin D1 in colorectal cancer, thereby promoting the ability of colorectal cancer stem cells to undergo self-renewal." (PMID 37218871, 2023). "Another study found that cyclin D1 was an unfavorable prognostic factor in colorectal cancer patients." (PMID 35242498, 2022). "Our results showed that Bcl-2 and Cyclin D1’s expression levels were remarkably decreased in all three colorectal cancer cell lines." (PMID 35879795, 2022). "In summary, this important finding further emphasized DDX39B can directly bind to its downstream CDK6 and CCND1 genes and upregulate their expression levels to promote the proliferation of the colorectal cancer cells." (PMID 35046400, 2022). "Our results demonstrated that roburic acid effectively suppressed colorectal cancer cell proliferation by inducing G0/G1 cell cycle arrest and downregulating the protein expression of Cyclin B1, Cyclin D1, and Cyclin E1." (PMID 35222445, 2022).
colorectal cancer (continued). "Studies have shown that upregulation of Cyclin D1 can promote the progression of various tumors, including endometrial cancer, liver cancer, and colorectal cancer." (PMID 36072972, 2022). "The downstream transcription factor cyclin D1 is positively regulated by Akt and mTOR, in which the degradation of cyclin D1 would accelerate the G1-phase cell cycle arrest in colorectal cancer cells." (PMID 36139789, 2022). "As a classical oncogene, CCND1 (cyclinD1) regulates the cell cycle to promote cancer progression and its role in colorectal cancer had been demonstrated in several studies." (PMID 36230970, 2022). "In conclusion, DDX39B acts as a colorectal cancer promoter through its effect on the CDK6/CCND1, which can promote the G1/S phase transition to enhance CRC proliferation." (PMID 35046400, 2022). "In colorectal carcinoma, miR-628-5p can downregulate CCND1 expression to induce apoptosis and restrain cell proliferation." (PMID 36118276, 2022). "Accumulating evidence illustrated that ITGB1 sustains cell proliferation through the upregulation of cyclin D1 in colorectal cancer cells and satellite cells." (PMID 34977001, 2021). "CDCA3 overexpression has been reported to promote the G1/S phase transformation and promote the proliferation of colorectal cancer cells by activating the NF-kB/cyclin D1 signaling pathway." (PMID 34239875, 2021). "It was also reported to decrease proliferation of colorectal cancer cells by repressing cyclin D1 transcription." (PMID 33640491, 2021). "TGM2-siRNA knockdown attenuated colorectal cancer cell growth through the wnt3a/β-catenin/cyclin D1 pathway." (PMID 34202278, 2021). "6-gingerol suppressed cyclin D1 expression, and EGCG has an antiproliferative effect on colorectal cancer cells through the degradation of cyclin D1 and the upregulation of p21." (PMID 33578780, 2021). "The results of RT-qPCR showed that the expression of cyclin D1 and c-myc mRNA was increased in colorectal carcinoma tissues compared with normal colon tissues." (PMID 34657551, 2021). "Very recently, cell-cycle-related and expression-elevated protein in tumor was found to transcriptionally enhance cyclin D1 expression to promote colorectal carcinoma cell replication likely by miR-383." (PMID 33402109, 2021). "An increase in NAG-1 expression was observed, whereas cyclin D1 expression level was decreased in all four colorectal cancer cell lines treated with A. oxyphylla." (PMID 32928152, 2020). "Cyclin D1 expression is high in colorectal cancer due to the abnormal adenomatous polyposis coli or β-catenin genes." (PMID 33379302, 2020). "PL-induced Cyclin D1 downregulation and tumor suppression in colorectal cancer cells by suppression of ERKs/Akt-mediated c-Fos expression." (PMID 33343354, 2020). "It is important in the initiation of colorectal cancer and SATB1 expression in colorectal cancer is associated with the expression of S100A4, MMP2, NF-kB, PCNA, cyclin D1 and β-catenin." (PMID 33356851, 2020). "It is revealed that STAT3 can regulate the expression of Cyclin D1 through directly targeting its promoter in colorectal cancer cells." (PMID 32194797, 2020). "The signaling molecules perturbed by CCRK are divergent and cancer-specific, including the cell cycle regulators CDK2, cyclin D1, cyclin E and RB in glioblastoma, ovarian carcinoma and colorectal cancer and lung cancer." (PMID 30846786, 2019). "Cyclin D1 overexpression has been observed in 63.6% of colorectal cancer and cyclin D1 has been known to be participated in the growth and differentiation of colorectal cancer." (PMID 30736789, 2019).
colorectal cancer (continued). "Patients with cyclin D1-positive expression colorectal cancer have a poorer prognosis and shorter survival." (PMID 30551667, 2018). "In this study, it was observed that cyclin D1 was downregulated by TY-NS-B treatment at both protein and mRNA level in human colorectal cancer cell lines such as HCT116 and SW480." (PMID 29925351, 2018). "TC-HW suppressed the proliferation of human colorectal cancer cells through GSK3β-dependent cyclin D1 degradation and induced ROS-dependent apoptosis in human colorectal cancer cells." (PMID 29554905, 2018). "Colorectal cancers often exhibit aberrant activation of the Wnt/ βcatenin pathway leading to activation of downstream oncogenic targets, such as cyclin D1, c-Myc and the intestinal stem cell regulatory gene, Lgr5." (PMID 30197752, 2018). "Kahweol-induced inhibition of cyclin D1 expression is presumed to be a chemoprevention for colorectal cancer." (PMID 30551667, 2018). "In this study, we observed that TC-HW downregulates cyclin D1 at both protein and mRNA level in human colorectal cancer cells." (PMID 29554905, 2018). "So far, several studies have demonstrated that high cyclin D1 expression was observed in cancers including breast, lung, prostate, lymph node and colorectal cancers." (PMID 28264020, 2017). "It has been distinguished that CCND1 gene is one of the main genes in Wnt signaling pathway which involves in generating colorectal cancer." (PMID 29511472, 2017). "For example, CCDN1 amplification and cyclin D1 overexpression have been reported to account for 2.5% and 55% in human colorectal cancer, respectively." (PMID 28870200, 2017). "The results imply that LRG1 modulates the cell cycle and cell proliferation of colorectal cancer by regulating the expression of cyclin D1, B, and E." (PMID 28376129, 2017). "In sum, we conclude that cyclin D1 downregulation appears as a primary mode of action whereby obatoclax provokes G1-phase cell cycle arrest, leading to antiproliferation of colorectal cancer cells." (PMID 28035994, 2016). "The clinical parameters and prognostic value for miR-374a and CCND1 in colorectal cancer were analyzed respectively." (PMID 27191497, 2016). "Cyclin D1 overexpression is a common molecular alteration in various types of human cancers and has been identified in 55%~68% of human colorectal cancer cases." (PMID 28035994, 2016). "Cyclin D1 is an important regulator of the cell cycle that is overexpressed in colorectal cancers as a consequence of activated TCF/β-catenin signaling." (PMID 26862734, 2016). "We herein reported that, in a panel of human colorectal cancer cell lines, obatoclax inhibits cell proliferation, suppresses clonogenicity, and induces G1-phase cell cycle arrest, along with cyclin D1 downregulation." (PMID 28035994, 2016). "Our results also demonstrated that sAPRIL-BP reduced the expression of CDK4 and cyclin D1 in a dose-dependent manner in the colorectal cancer LOVO cell line." (PMID 25826583, 2015). "It has also been reported that nuclear β-catenin and cyclin D1 are co-overexpressed in the invasion front of colorectal cancer." (PMID 25605017, 2015). "Another study reported that nonsteroidal anti-inflammatory drugs (NSAIDS) inhibit TCF-1/β-catenin mediated downstream target genes such as cyclin D1 and thereby inhibits growth of colorectal cancer cells." (PMID 25869100, 2015).